FOXM1 (forkhead box M1)
Diseases named in the same sentence as FOXM1 in open-access papers (continued):
Sharing a sentence is not in itself a finding about the gene and the disease.
osteosarcoma (42 papers, 2009 to 2025). A usually aggressive malignant bone-forming mesenchymal neoplasm, predominantly affecting adolescents and young adults. "We next tested the effects of mutations to the NRD-TAD interface on FoxM1 activity in U2OS osteosarcoma cells using a luciferase reporter assay." (PMID 31134895, 2019). "Knockdown of FOXM1 causes increased cellular senescence of mAKT1 expressing osteosarcoma cells and deletion of FOXM1 can diminish cancer cell invasion, migration and angiogenesis." (PMID 27074562, 2016). "Not long after, another team confirmed that the MEG3/miR-361-5p/forkhead box M1 (FoxM1) signaling axis may be a diagnostic biomarker or therapeutic target for osteosarcoma." (PMID 36544907, 2022). "For example, one bioinformatics study identified the oncogenic function of FoxM1 and its association with TME, prognosis, and drug resistance in osteosarcoma." (PMID 39324133, 2024). "FOXM1 expression is significantly increased in osteosarcoma, and FOXM1 decreases tumor formation, proliferation, migration, and invasion." (PMID 39086352, 2024). "SPAG5 silencing inhibited migration, invasion, and epithelial-mesenchymal transition of osteosarcoma cells, which is attributed to regulating the FOXM1/MMP2 axis." (PMID 38807081, 2024). "On the contrary, it was also evident that miR-370 was reduced in Osteosarcoma cells where FOXM1 expression was elevated." (PMID 37081847, 2023). "Except for miR-361, its downstream genes, such as vascular endothelial growth factor (VEGF), forkhead box protein 1(FOXM1), and Twist, were also suppressed in osteosarcoma cells, resulting in EMT and tumour growth." (PMID 37636269, 2023). "In support of our data, it was delineated that the interaction of β-catenin with forkhead box protein M1 (FOXM1) mediates osteosarcoma cell growth and metastasis." (PMID 35676319, 2022). "Overexpression of lncRNA FOXD2-AS1 promotes the progression of osteosarcoma by targeting forkhead box M1 (FOXM1)." (PMID 36139062, 2022). "Our microarray results revealed only FOXM1 as a differentially expressed transcription factor in osteosarcoma cells." (PMID 33391445, 2021). "In osteosarcoma, FOXM1 and β-catenin directly interact to promote TCF4 binding to the Wnt gene promoter, enhancing Wnt activity." (PMID 32035486, 2020). "In osteosarcoma cells, FOXM1 was also known to transcriptionally regulate the expression and phosphorylation c-Jun N-terminal kinase (JNK1) to drive cell proliferation." (PMID 31390744, 2019). "Ixazomib inhibits the transcriptional activity of FOXM1 using a luciferase reporter osteosarcoma cell line with inducible FOXM1." (PMID 30089730, 2018). "Interruption of FOXM1 reduced the survivin expression in leukemia and osteosarcoma cell lines and inhibited cell-cycle progression." (PMID 27439614, 2016). "Preclinical studies that ablate FOXM1 by RNA interference have demonstrated decreased cellular proliferation in numerous types of cancer including osteosarcoma." (PMID 27074562, 2016). "In preclinical experiments this synthetic peptide suppressed FOXM1 induced colony growth of U2OS osteosarcoma cells and suppressed FOXM1 transcriptional activity." (PMID 27074562, 2016). "In addition, it had been reported that N6-methyladenosine methyltransferase WTAP-stabilized FOXD2-AS1 promoted the osteosarcoma progression through m6A/FOXM1 axis." (PMID 39397896, 2024). "Of note, heightened FOXM1 expression in osteosarcoma correlates with decreased response to immunotherapy, bolstering the possibility that inhibition of FOXM1 may be key to preventing ICB therapy resistance in our sarcoma model of MPNST." (PMID 39347707, 2024). "The signaling pathways involved in tumor progression of Osteosarcoma are the FOXM1 transcription pathway, ATM signaling pathway, FAK mediated signaling events, Arf6 signaling events, Class 1 PI3K signaling events, mTOR signaling pathway, and Integrin family cell surface interactions." (PMID 37081847, 2023).
osteosarcoma (continued). "Thus, micro-RNA can serve as a potential drug target in controlling the spread of Osteosarcoma by FOXM1 factor since the contribution of this transcription factor in promoting the disease is exemplary." (PMID 37081847, 2023). "Moreover, it has been reported that SPAG5 contributes to metastasis of osteosarcoma by activating FOXM1/MMP2 signaling." (PMID 35342412, 2022). "In addition, the activation of the AKT pathway promoted the expression of lncRNA TUG1 by up-regulating the expression of FOXM1, forming a positive feedback loop in osteosarcoma." (PMID 34039257, 2021). "Forkhead Box M1 (FOXM1) up-regulated the expression of lncRNA TUG1 in osteosarcoma cells." (PMID 34039257, 2021). "It was reported that MIR31HG could directly sponge to tumor suppressor- miR-361, rather than miR-31, and in turn regulate cell proliferation, cell cycle arrest, and apoptosis via targeting VEGF, FOXM1 and Twist in osteosarcoma." (PMID 32280307, 2020). "Studies have shown that in osteosarcomas, FoxM1 and β-catenin directly bind to the cytoplasm and nucleus, enhancing the nuclear transcription of β-catenin, promoting its binding with TCF4 on the Wnt target gene promoter, enhancing the activity of the Wnt pathway." (PMID 32035486, 2020). "This review infers that certain sarcoma subtypes such as Ewing sarcoma and osteosarcoma may be particularly ‘druggable’ using FOXM1 inhibition." (PMID 27074562, 2016). "Increased levels of FOXM1 expression have been detected in many different types of human cancer and sarcoma such as rhabdomyosarcoma, Ewing sarcoma, malignant peripheral nerve sheath tumor, and osteosarcoma." (PMID 27439614, 2016). "In osteosarcoma, diallyl disulfide (DADS) inhibits FOXM1 expression by activating miR-134, an upstream regulator of FOXM1, thereby reducing cancer cell proliferation and invasion." (PMID 40612352, 2025). "In the present study, we revealed that CtBP1 directly interacted with FOXM1, and that the complex docked onto the MDR1 promoter through a specific binding site (5′-GTAAACAA-3′) to activate MDR1 expression in osteosarcoma CSCs." (PMID 33391445, 2021). "Our recent study suggested that AKR1C1 is a novel target of FoxM1 and FoxM1/AKR1C1 signaling is inhibited by avasimibe at osteosarcoma." (PMID 34127944, 2021). "SRSF3 has been recently reported to regulate alternative splicing and gene expression of forkhead box M1 (FoxM1), polo-like kinase 1 (PLK1), and cell division cycle 25B (Cdc25B) in U2OS osteosarcoma cells." (PMID 28039456, 2017). "C3-Luc2.3-FoxO1 cells are a derivative of U2OS osteosarcoma cells with a doxycycline-inducible FoxM1-GFP fusion protein, a tamoxifen-inducible constitutively active FoxO1(AAA)-ER fusion protein and a FoxM1/FoxO1-dependent firefly luciferase." (PMID 19440351, 2009). "To investigate the potential role of FoxM1 in the thiopeptide-mediated apoptosis, we treated U2OS osteosarcoma cells with 10 μM of Siomycin A and harvested the cells at different time points." (PMID 19440351, 2009). "In osteosarcoma, the WTAP/FOXD2-AS1/m6A/FOXM1 axis promotes osteosarcoma progression." (PMID 38351139, 2024). "Furthermore, overexpression of MIR31HG promoted tumour growth in osteosarcoma cells by downregulating miR-361 expression and elevating the expression of VEGF, FOXM1 and Twist, which are target genes of miR-361." (PMID 37636269, 2023). "The group of Li demonstrated that ectopic expression of Forkhead Box M1 (FOXM1) led to upregulation of TUG1 in osteosarcoma cell lines while a mutant form of FOXM1 did not influence TUG1 levels." (PMID 31973032, 2020). "This agrees with a previous study showing FOXM1 protein stabilisation, rather than de novo mRNA expression, following UV, ionizing irradiation and Etoposide treatment in a human osteosarcoma U2OS cancer cell line." (PMID 20187950, 2010).
osteosarcoma (continued). "Importantly, the knockdown of either CtBP1 or FOXM1 and targeting of the CtBP1-FOXM1 complex members with specific inhibitors, including NSM0018 and NSC95397 for CtBP1, and RCM1 for FOXM1, significantly decreased the MDR1 level and increased the chemosensitivity of osteosarcoma CSCs." (PMID 33391445, 2021).
diabetes (40 papers, 2011 to 2026). "Given the important role of FOXM1 in diabetes and its associated complications, we investigated the effects of FOXM1 in HG-induced cell injury." (PMID 40514721, 2025). "Thus, FOXM1 emerges as a pivotal regulator in the modulation of these crucial signaling cascades and molecular mechanisms underlying the development of diabetes and its associated complications." (PMID 40514721, 2025). "Based on our findings, inhibition of FOXM1 further delayed healing in the context of diabetes, suggesting that the presence of diabetes may increase the susceptibility to FOXM1 inhibition." (PMID 32938916, 2020). "Furthermore, FOXM1-deficient mice exhibited reduced insulin secretion, whereas the activation of FOXM1 increased β-cell replication, enhanced insulin production, and improved glucose balance, rendering FOXM1 an appealing target for the management of diabetes." (PMID 37238726, 2023). "In our study, the molecular underpinnings of endothelial dysfunction in diabetes are investigated, focusing on the roles of disabled-2 (Dab2) and Forkhead box M1 (FOXM1) in VEGF receptor 2 (VEGFR2) signaling and endothelial cell function." (PMID 39846251, 2025). "Although previous studies have suggested an involvement of FOXM1 in the pathogenesis of diabetes, emerging studies have revealed that deletion of FOXM1 in diabetic mice impairs wound healing, in part, via impeded recruitment of immune cells." (PMID 39846251, 2025). "Forkhead box M1 (FoxM1) transcription factor affects pancreatic adult beta cell proliferation, and naringin increases beta cell mass and treats diabetes by upregulating FoxM1." (PMID 38399736, 2024). "In particular, FOXM1 is involved not only in human diabetes and its complications but also in the advancement of β-cell proliferation and wound healing." (PMID 37238726, 2023). "FOXM1 expression is involved in the development or repair of multiple diseases, including pulmonary fibrosis, pneumonia, diabetes, liver injury repair, adrenal lesions, vascular diseases, brain diseases, arthritis, myasthenia gravis, and psoriasis." (PMID 37238726, 2023). "Mice that were deficient in FOXM1 in the pancreas exhibited glucose tolerance or diabetes and had a 60% decrease in β-cell mass, indicating that the deletion of FOXM1 is detrimental to β-cell function." (PMID 37238726, 2023). "In terms of diabetes and its complications, the regulation of FOXM1 can improve insulin resistance and insulin secretion and reduce the occurrence and development of diabetes." (PMID 37238726, 2023). "YAP/FOXM1 is considered an effective target axis for improving the remission of functional β-cell disease in patients with diabetes." (PMID 37238726, 2023). "This article also reviews the roles of FOXM1 in the treatment and occurrence of lung diseases, liver diseases, kidney diseases, brain-, cardio-, bone-, and skin-related diseases, diabetes, and other diseases as a therapeutic target with broad prospects." (PMID 37238726, 2023). "The increase in TREM1 promotes FoxM1-positive neutrophil recruitment, reverses the effects of diabetes, and promotes wound healing in the body." (PMID 37238726, 2023). "The antifibrotic function of Foxm1 has been reported in cardiac hypertrophy and fibrosis, diabetes, and pulmonary fibrosis." (PMID 30378114, 2019). "Although previous studies acknowledge the pivotal role of FOXM1 in diabetes-related cellular functions and β cell proliferation, our study delves into the mechanistic interaction between FOXM1 and Dab2 within the context of ECs and angiogenesis during diabetic wound healing." (PMID 39846251, 2025). "FOXM1 is downregulated in diabetes and regulates Dab2 transcription." (PMID 39846251, 2025). "The signal transducer and activator of transcription 1 protein (STAT 1) binds to the FoxM1 promoter (Forkhead box M1 protein) and contributes to diabetes by increasing the expression of genes involved in cell proliferation, fibrosis, inflammation and oxidative stress." (PMID 39728417, 2024).
diabetes (continued). "Thus, mitotic cell cycle progression, regulated by the FOXM1 pathway, is important in delaying β-cell adaptation and/or preventing progression to diabetes." (PMID 37238726, 2023). "The roles of FOXM1 in human diseases such as diabetes and its complications, inflammation, fibrosis, psoriasis, and myasthenia gravis, as well as longevity, are detailed below, as this is a key cellular regulator and transcription factor that is involved in regulating biological processes." (PMID 37238726, 2023). "Due to genetic differences, FOXM1 expression is involved in the development or repair of multiple diseases, including pulmonary fibrosis, pneumonia, diabetes, liver injury repair, adrenal lesions, vascular diseases, brain diseases, arthritis, myasthenia gravis, and psoriasis." (PMID 37238726, 2023). "Forkhead box M1 (Foxm1) is a transcription factor best‐recognized as a master regulator of physiological and pathological processes, including cancer, diabetes mellitus, and fibrosis‐related disease." (PMID 30378114, 2019). "In addition to the occurrence and development of tumors, FOXM1 plays important regulatory roles in the growth and development of diabetes and occurrence and development of kidney, vascular, lung, brain, bone, heart, skin, and blood vessel diseases, as well as tissue damage repair." (PMID 37238726, 2023). "Moreover, FOXM1 has been implicated in the pathogenesis of diverse non-neoplastic disorders including pulmonary fibrosis and Maturity-Onset Diabetes." (PMID 37344857, 2023). "The insulin-FOXM1/PLK1/CENP-A signaling pathway is able to mitigate beta cell damage and/or prevent diabetes progression by regulating β-cell cycle processes." (PMID 37238726, 2023). "By injecting Dab2 mRNA encapsulated in lipid nanoparticles (LNPs), or using the FOXM1 inhibitor FDI-6, wound healing was significantly enhanced through increased angiogenesis, which could lay the foundation for the development of novel therapies to enhance angiogenesis in diabetes." (PMID 39846251, 2025).
pulmonary fibrosis (37 papers, 2015 to 2026). Chronic progressive interstitial lung disorder characterized by the replacement of the lung tissue by connective tissue, leading to progressive dyspnea, respiratory failure, or right heart failure. "On the other hand, the transfer of FOXM1-expressing monocytes protects FOXM1-deficient mice against lung fibrosis." (PMID 37569370, 2023). "Studies have shown that interference with FOXM1 in fibroblasts or the administration of FOXM1 inhibitors reduces the expression of bleomycin-induced pulmonary-fibrosis-associated factors." (PMID 37238726, 2023). "Macrophage-specific loss of function of forkhead box M1 (a p38 signaling pathway inhibitor) exacerbates BLM-induced pulmonary fibrosis." (PMID 36998607, 2023). "Adoptive transfer of FOXM1-expressing monocytes protected FOXM1-deficient mice from bleomycin-induced pulmonary fibrosis." (PMID 32271749, 2020). "FOXM1, a transcription factor linked to pulmonary diseases, may influence cell cycle transitions and has associations with lung injury repair and the development of pulmonary fibrosis." (PMID 37887346, 2023). "Further, downregulation of SIRT3 expression enhances the stability of FoxM1, thereby accelerating bleomycin-induced pulmonary fibrosis through the activation of pulmonary fibroblasts." (PMID 41797045, 2026). "We observed the senolytic effect of the FoxM1 inhibitor thiostrepton on bleomycin-induced lung fibrosis in mice." (PMID 41392167, 2025). "For instance, one study showed that Foxm1 deletion in fibroblasts ameliorates lung fibrosis; however, another study showed that Foxm1 deletion in macrophages appears to promote lung fibrosis." (PMID 38916959, 2024). "In a mouse model of silica-induced pulmonary fibrosis, ALKBH5 promoted lung fibroblast activation and silica-induced pulmonary fibrosis via the miR-320a-3p/FOXM1 axis or targeting FOXM1 directly." (PMID 39220683, 2024). "Our findings contrast with those from other studies describing that Foxm1 inhibition ameliorates renal fibrosis and lung fibrosis." (PMID 38916959, 2024). "The expression of FOXM1 was found to be increased in idiopathic pulmonary fibrosis (IPF) patients and bleomycin-induced mouse lung fibroblasts." (PMID 37238726, 2023). "Pulmonary fibrosis was significantly lower in LPS + BMSCs-Vector and LPS + BMSCs-FoxM1 groups relative to the LPS group." (PMID 36788588, 2023). "FOXM1 plays a major role in regulating the development of lung fibrosis by inducing the expression of the proliferation-related genes CCNB1, CCND1, and PLK1." (PMID 37238726, 2023). "This article reviewed the roles of FOXM1 in various diseases, particularly chronic progressive diabetes, pulmonary fibrosis, and organismal aging." (PMID 37238726, 2023). "In conclusion, in radiation-induced pulmonary fibrosis, FOXM1 is mediated by the activation of lung inflammation and expression of EMT-related genes." (PMID 37238726, 2023). "It is worthwhile mentioning here that previous studies revealed that FOXM1 inhibition in fibroblasts and epithelial cells has a protective effect on lung fibrosis." (PMID 37681924, 2023). "The expression of lncRNA PVT1 can be enhanced by FOXM1, a profibrotic factor, leading to excessive pulmonary fibrosis." (PMID 37367427, 2023). "FOXM1 is a key factor in promoting the progression of pulmonary fibrosis and a key target in blocking the progression of fibrosis in lung tissue or other tissues and organs." (PMID 37238726, 2023). "In conclusion, FOXM1 has been identified as a critical driver and regulator of lung fibrosis activation due to various factors, and the potential for targeting FOXM1 in the treatment of pulmonary fibrosis has been clarified." (PMID 37238726, 2023). "A high expression of FOXM1 in vascular endothelial cells enhanced the expression of radiation-pneumonia- and pulmonary-fibrosis-related factors." (PMID 37238726, 2023).